BRCA2 (BRCA2 DNA repair associated)
Diseases named in the same sentence as BRCA2 in open-access papers (continued):
Sharing a sentence is not in itself a finding about the gene and the disease.
melanoma (continued). "Interestingly, 2 out of 7 acral melanoma subjects responded to JS001 treatment (1CR and 1PR), and both harbored EMSY gene amplification, which was suggested to be functionally equivalent to somatic BRCA2 loss-of-function mutations." (PMID 30642373, 2019). "Therefore, we investigated whether additional candidate genes, such as BRCA2 and MC1R, might play a role in melanoma susceptibility within such an isolated population." (PMID 19799798, 2009). "Taken together, this suggests that melanoma risk may be elevated in specific BRCA2 families, but not for all BRCA2 carriers." (PMID 17213823, 2007). "In addition to melanoma susceptibility genes, an increased risk of melanoma has been reported in patients with germline mutations causing cancer syndromes, including hereditary breast and ovarian cancer (BRCA1/BRCA2), Werner syndrome (WRN), and xeroderma pigmentosum (XP)." (PMID 38028607, 2023). "Another study demonstrated that LOXL3 interacted with proteins involved in DNA stability (e.g., BRCA2 and SMC1A) and mitosis completion to accelerate the proliferation of melanoma cells." (PMID 34307505, 2021). "Early studies of women who carry BRCA mutations found an increased risk of melanoma in family members of BRCA2 carriers However, this was not seen in a recent study of BRCA1 and BRCA2 families described by the CIMBA consortium." (PMID 38741145, 2024). "Therefore, we analyzed gene expression of the important HRR genes BRCA1, BRCA2, RAD51, and EXO1 after MAPKi treatment in MAPKi S, R, and RR A375 melanoma cells." (PMID 37674529, 2023). "Of the two, BRCA2 has traditionally been described with a stronger, albeit still relatively weak, link to melanoma development, though recent data indicates neither BRCA1 nor BRCA2 are likely to have a significant impact on the melanoma risk." (PMID 34638397, 2021). "CTAG1B, BRCA2, and SPAG8 have been previously shown to induce humoral immune response in BC and other cancer patients, ANKRD30BL and COPS4 were previously found to elicit autoantibody response in gastric and thyroid cancer and melanoma." (PMID 30515157, 2018). "A previous study showed that filamin-A interacts with BRCA2, and lack of filamin-A expression results in increased cellular sensitivity to several DNA-damaging agents in melanoma cells." (PMID 19367286, 2009). "In addition, the most recurrent BRCA2 PV in Sicilian female population with HBOC, named 1466delT (HGVS nomenclature: c.1238del; p.Leu413fs), has been observed with very low frequency in men affected by MBC, PCa, PC or melanoma." (PMID 38974244, 2024). "Furthermore, a recent study discovered that dual inhibition of BRAFV600E and MEK with dabrafenib and trametinib potently suppressed the expression of several genes of the homologous repair pathway in a subset of melanoma cell lines, including BRIP1, BRCA2, EME1 and RBBP8." (PMID 33800547, 2021). "A highly significant overlap of transcript expression in melanoma cell lines after cisplatin treatment with transcripts involved in DNA repair and DNA damage response genes BRCA1, BRCA2, ATM and CHEK2 was observed, which may be compensating for diminished NER capacity." (PMID 23940574, 2013).
triple-negative breast carcinoma (111 papers, 2009 to 2026). An invasive breast carcinoma which is negative for expression of estrogen receptor (ER), progesterone receptor (PR), and human epidermal growth factor receptor 2 (HER2). "The patient with the detected BRCA2 methylation in the pleural metastasis as well as in the associated xenograft was diagnosed with a triple-negative breast carcinoma in 2016 at the age of 25." (PMID 39392573, 2025). "This is also supported by prior work showing upregulation of type I IFN in a PDX model of Brca2 WT triple-negative breast cancer at higher olaparib doses than in a BRCA1-mutated PDX model." (PMID 40579444, 2025). "We generated hypomorphic BRCA1 and BRCA2 variants of the HRR proficient triple negative breast cancer cell line MDA-MB-231." (PMID 39819384, 2025). "About 20% of patients with triple-negative breast cancer present mutation in the BRCA1 or BRCA2 genes, which are essential to the repair of double-strand DNA breaks by homologous recombination repair." (PMID 38506114, 2024). "Somatic mutations in BRCA1 are more commonly associated with basal-like and triple-negative breast cancers, while somatic BRCA2 mutations can lead to various subtypes, including luminal and TNBC." (PMID 39272660, 2024). "Other studies have shown that luminal A has a prevalence of 49% in PIK3CA mutations, while BRCA1 and BRCA2 mutations are characteristic of triple negative breast cancer." (PMID 39264897, 2024). "Germline mutations in the BRCA1 and BRCA2 genes are reported in about 15–20% of all triple-negative breast cancers." (PMID 38785549, 2024). "Protein-truncating variants in BRCA2 were strongly associated with an increased risk of ER-positive and triple-negative breast cancer with adjusted ORs of 10.18 (1.77-58.55 95% CI, p-value = 0.009) and 10.14 (1.08-94.84 95% CI, p-value = 0.042), respectively." (PMID 37790698, 2023). "Just as BRCA1 mutation is more common in triple negative breast cancer, whereas BRCA2 mutations are more common in Luminal B breast cancer." (PMID 35509067, 2022). "Poly-(ADP)-ribose polymerase inhibitors (PARPi) and platinum-based drugs are promising therapies for triple negative breast cancers (TNBC) with BRCA1 or BRCA2 loss." (PMID 34367977, 2021). "By contrast, triple-negative breast cancer was more common among women with BRCA1 than BRCA2 mutations (28.38% vs. 7.46%)." (PMID 33649363, 2021). "Approximately 25% of patients diagnosed with triple negative breast cancer carry a germline BRCA1 or BRCA2 mutation." (PMID 34900718, 2021). "More recently, defects in the homologous recombination system, such as BRCA1 and BRCA2 mutations have been associated with higher rates of response to platinum-based and anthracyclines regimens both in triple negative breast cancers (TNBCs) and EOCs." (PMID 30760286, 2019). "Differences in tumour characteristics between BRCA1 and BRCA2 mutation carriers were also noted in patients with triple-negative breast cancer." (PMID 29337092, 2018). "It had shown promising therapeutic effects in BRCA2 mutation-carrier patients with triple-negative breast cancer and sporadic serous ovarian cancer in females and CRPC and metastatic PCa in males." (PMID 28410213, 2017). "Ovarian and triple-negative breast cancers with BRCA1 or BRCA2 loss are highly sensitive to treatment with PARP inhibitors and platinum-based cytotoxic agents and show an accumulation of genomic scars in the form of gross DNA copy number aberrations." (PMID 26015868, 2015). "It is well established that families carrying a germline BRCA1 mutation have increased incidence of basal-like/triple-negative breast cancers, while germline BRCA2 mutations predispose to cancers of the lumB subtype." (PMID 24479546, 2014). "The aim of this study was to investigate the role of BRCA2 germline mutations in triple-negative breast cancer (TNBC)." (PMID 22666503, 2012).
triple-negative breast carcinoma (continued). "Deleterious mutations of the second breast cancer susceptibility gene, BRCA2, have also been reported to occur at a high frequency in German patients with triple-negative breast cancers." (PMID 23110154, 2012). "In fact, we have recently initiated a Phase II clinical trial for gemcitabine, carboplatin and PARP inhibitor iniparib (BSI-201) in the neoadjuvant treatment of BRCA1 or BRCA2 mutated and triple-negative breast cancer." (PMID 21771338, 2011). "Five deleterious BRCA1 mutations and one deleterious BRCA2 mutation were identified in the 54 patients with early-onset, triple-negative breast cancer (11%)." (PMID 19298662, 2009). "A recent study evaluated BRCA1 promoter methylation by quantitative methylation-specific PCR and demonstrated that triple-negative breast cancer (TNBC) patients with a BRCA1 or BRCA2 mutation, or high BRCA1 promoter methylation, showed better 6-month PFS compared with the other patients (p = 0.009)." (PMID 40075848, 2025). "The aim of this study was to conduct an in silico analysis of a novel compound heterozygous variant in breast cancer susceptibility gene 2 (BRCA2) to clarify its structure–function relationship and elucidate the molecular mechanisms underlying triple-negative breast cancer (TNBC)." (PMID 38773604, 2024). "To determine whether combination of olaparib and everolimus is synergistic in BRCA2 mutated cells, we performed drug combination cell viability assays in two triple-negative breast cancer cell lines, HCC1395 (BRCA2 mutated) and BT20 (PI3KCA mutated)." (PMID 30038706, 2018). "BRCA1 and BRCA2 mutation carriers are frequently diagnosed with triple-negative breast cancer." (PMID 22666503, 2012). "While inherited BRCA1/BRCA2 mutations drive hereditary risk, recent evidence highlights the critical role of BRCA1 promoter methylation especially in sporadic and triple-negative breast cancers (TNBC), which disproportionately affect African-descended women." (PMID 41836332, 2026). "To test this we selectively targeted the BRCA1 and BRCA2 loci in the HRR proficient triple negative breast cancer cell line MDA-MB-231 (M231wt), using standard CRISPR-Cas9 techniques to generate an isogenic cell line panel." (PMID 39819384, 2025). "Suppose women have a history of unmarried and childless, family inheritance, triple-negative breast cancer, postoperative oral selective estrogen antagonist, and BRCA1/BRCA2 gene mutation." (PMID 40530017, 2025). "Most triple-negative breast cancers (TNBC) are sporadic in nature and often associated with dysfunction of the BRCA1 or BRCA2 genes." (PMID 39392573, 2025). "It was observed that a higher proportion of BRCA1 carriers had the triple-negative breast cancer subtype, whereas more BRCA2 carriers exhibited estrogen receptor (ER) + and progesterone receptor (PR) + subtypes." (PMID 38167124, 2024). "PI3K inhibition is also sufficient to reduce BRCA1 and BRCA2 expression, hampering HR repair in triple-negative breast cancer." (PMID 37370140, 2023). "The frequency of pathogenic variants in women with triple negative breast cancer was 23.2%, with 91% of the observed pathogenic variants detected in BRCA1, BRCA2, and PALB2." (PMID 36544278, 2023). "In our cohort, we found an enrichment of triple-negative breast cancers in BRCA1 mutation carriers and hormone receptor-positive cancers in BRCA2 mutation carriers." (PMID 33649363, 2021). "Recently, a new class of molecules has emerged as a standard of care for patients with triple negative breast cancer and germline BRCA1 or BRCA2 mutation: poly (ADP-ribose) (PARP) inhibitors." (PMID 34900718, 2021). "In another study, neoadjuvant chemotherapy was associated with a higher rate of pathological complete response in BRCA1 and BRCA2 carriers than in other patients with triple-negative breast cancer." (PMID 32939053, 2020).
triple-negative breast carcinoma (continued). "We observed a significant difference in the proportion of triple-negative breast cancer phenotype among 88.9%, 72.5%, and 26.8% of BRCA1 L63X mutation, BRCA1 mutation, and BRCA2 mutation carriers, respectively (p < .001)." (PMID 31143373, 2019). "In unselected triple negative breast cancers, around 19% mutations were reported in the BRCA1/2 genes including also scattered somatic mutations (15% in BRCA and 3.9% in BRCA2 genes)." (PMID 29453630, 2018). "In selected triple negative breast cancer cases, 57% were found to have BRCA1 and 23% BRCA2 germ line mutations." (PMID 29453630, 2018). "Among 359 patients with triple-negative breast cancer, 101 (28.3%) had mutations for BRCA1 and 18 (5.0%) for BRCA2." (PMID 30203341, 2018). "In contrast, of 425 screens in women with triple negative breast cancer, 151 (35.5%) resulted in positive BRCA tests with 117 (27.5%) having BRCA1 mutations and 34 (8.0%) BRCA2 mutations." (PMID 27796713, 2017). "PARP inhibitors have been studied most extensively in HSOC and triple-negative breast cancer, and have proven particularly effective against cancers associated with BRCA1 or BRCA2 mutations." (PMID 27613518, 2016). "The frequency of triple-negative breast cancer was 71.4% (5/7) in BRCA1 mutation carriers and 9.1% (1/11) in BRCA2 mutation carriers." (PMID 25927356, 2015). "In some cancers, e.g. triple-negative breast cancer, DNA instability is an integral part of the process of tumorigenesis, and is driven by defects in DNA repair systems (e.g. mutations in BRCA1 or BRCA2), which result in further cancer-driving mutations." (PMID 25252808, 2014). "In the present study, we scanned the whole coding regions of BRCA1, BRCA2, PALB2 and BRD7 in order to investigate the relative contributions of germ-line mutations in these genes to triple-negative breast cancer in a hospital-based series of German patients." (PMID 23110154, 2012). "Patients with triple-negative breast cancer without BRCA1 or BRCA2 mutations can benefit from immune checkpoint inhibitors." (PMID 38506114, 2024). "The results indicate better overall survival in young triple-negative patients with pathogenic germline variants in BRCA1 or BRCA2 compared to triple-negative breast cancer without pathogenic variants, but not for other clinical subtypes." (PMID 38398129, 2024). "Approximately 10% to 15% of triple-negative breast cancers (TNBC) have deleterious mutations in BRCA1 and BRCA2 and may benefit from PARP inhibitor treatment." (PMID 37773077, 2023). "Furthermore, rare missense variants within PALB2 domains WD1, domain for stimulation of POLH DNA synthesis and domain for interaction with RAD51, BRCA2 and POLH were significantly associated with increased risk of triple-negative breast cancer." (PMID 37790698, 2023). "BRCA2 mutations were also more frequent in the triple negative breast cancer and HR+ HER2- subtypes, although these trends were not significant." (PMID 35494038, 2022). "BRCA1 carriers have earlier-onset disease, particularly under age 50 and are more likely to develop aggressive triple-negative breast cancer than BRCA2 carriers or those who are BRCA mutation negative." (PMID 34228231, 2021). "Pathogenic germline mutations in BRCA1, BRCA2, PALB2, RAD51C, and RAD51D, all of which are involved in the HR pathway, are known to confer high or moderate penetrance susceptibility to ovarian and/or triple-negative breast cancer." (PMID 34635660, 2021). "BRCA1 carriers were more likely to be triple negative breast cancer compared to BRCA2 carriers." (PMID 34490083, 2021). "Moreover, the loss of ARH3 increased PARPi resistance in triple-negative breast cancer (TNBC) SUM149PT (BRCA1 mutant, BRCA2-WT) and SUM159PT (BRCA1/2-WT) cells." (PMID 34019811, 2021).
triple-negative breast carcinoma (continued). "Triple negative breast cancer (TNBC) may have diverse defects in HR DNA repair, through germline mutations in BRCA1, BRCA2 and PALB2, somatic mutations in BRCA1 and BRCA2, promoter methylation of BRCA1 and RAD51C, and other as yet to be identified mechanisms." (PMID 32471999, 2020). "Therapy options for triple-negative breast cancer are limited and decreasing innate olaparib resistance by BRCA2 downregulation could reveal a new path to more effective treatment." (PMID 26959114, 2016). "Likewise, mutations in BRCA1, BRCA2, PALB2, and other components with the HR pathway are common in familial and certain subtypes of sporadic breast cancer, particularly triple negative breast cancer (91–, 93)." (PMID 24062981, 2013). "We investigated a hospital-based series of 40 consecutive patients with triple-negative breast cancer for mutations in the whole coding sequences of BRCA1 and BRCA2 as well as in the two genes PALB2 and BRD7, which encode interaction partners of the BRCA1 protein." (PMID 23110154, 2012). "Triple negative breast cancers (TNBC) are ER−/PR−/HER2− with mesenchymal, basal-like, and claudin-low characteristics often carrying mutations in the tumor suppressor BReast CAncer 1 (BRCA1) and BReast CAncer 2 (BRCA2) genes, which play an important role in DNA repair." (PMID 34207792, 2021). "Neoadjuvant olaparib did not improve pCR rates, EFS or OS when added to carboplatin–paclitaxel and anthracycline-based chemotherapy in patients with triple-negative breast cancer who were germline BRCA1 and BRCA2 wild type." (PMID 38588696, 2024). "A study details the results of the PARTNER trial, a prospective, randomized controlled trial of the use of neoadjuvant olaparib with carboplatin–paclitaxel chemotherapy in patients with triple-negative breast cancer who were germline BRCA1 and BRCA2 wild type." (PMID 38588696, 2024). "The other cohort (reported here) consisted of patients with triple-negative breast cancer (TNBC) who were germline BRCA1 and BRCA2 wild type (gBRCAwt))." (PMID 38588696, 2024). "TNBCs (triple negative breast cancers, ER-, PR-, and HER2-) were more commonly found in carriers with BRCA1, BRCA2 or PALB2 PVs." (PMID 35135604, 2022). "Next, two triple negative breast cancer (TNBC) cell lines, BT-549 and MDA-MB-231, were depleted for BRCA2." (PMID 30626869, 2019). "NUSAP1 expression was correlated with BRCA1, BRCA2, and BARD1 expression, and upregulation of NUSAP1 predicted poor prognosis in triple-negative breast cancer." (PMID 30678687, 2019). "To extend our investigations into a more clinically relevant context, we tested the effect of IFNβ treatment on pancreatic adenocarcinoma cells (CAPAN-1) and triple-negative breast cancer cells (SUM149PT and MDA-MB-436) carrying BRCA1 or BRCA2 defects and we invariably obtained the same result." (PMID 37783689, 2023). "The Treating to New Targets trial did not demonstrate a role for HRD testing to identify patients with wild-type BRCA1 and BRCA2 who have advanced triple-negative breast cancer more likely to benefit from carboplatin as opposed to taxane chemotherapy." (PMID 36253484, 2022). "We used a pair of triple-negative breast cancer cell lines (MDA-MB 231-BRCA1wt vs MDA-MB 436-BRCA1KO), a set of wt mouse embryonic fibroblast (MEF) (shSCR vs shBRCA1), a hamster BRCA2 KO cell line with its reconstituted counterpart (V-C8 vs VC#13) and a pair HCT116 cells (shSCR vs shBRCA2)." (PMID 30705406, 2019). "Additionally, cluster 2 was also significantly associated with gender (p = 0.015), HER2 positive (p < 0.001), and triple-negative breast cancer (p = 0.005), but not BRCA1, BRCA2, ER, and PR (p > 0.05)." (PMID 34650974, 2021).